TYRP1 (tyrosinase related protein 1)
Diseases named in the same sentence as TYRP1 in open-access papers (continued):
Sharing a sentence is not in itself a finding about the gene and the disease.
vitiligo (19 papers, 2012 to 2024). Generalized well circumscribed patches of leukoderma that are generally distributed over symmetric body locations and is due to autoimmune destruction of melanocytes. "rs11614913 C allele in miR-196a-2 protect against oxidative effects on human melanocytes through regulating its target gene TYRP1 (tyrosinase-related protein 1), decreasing the risk of vitiligo." (PMID 36187493, 2022). "Taken together, rs11614913 polymorphism of miR-196a-2 is associated with the development of vitiligo by affecting the expression of Tyrp1 and tyrosinase." (PMID 36187493, 2022). "Additionally, using an immortalized human vitiligo melanocyte cell line, both cytoplasmic Hsp70 and Hsp90 were found to be translocated into apoptotic bodies along with autoantigens (e.g., tyrosinase-related protein 1 or cleavage nuclear membrane antigen Lamin A/C) associated with vitiligo." (PMID 36009046, 2022). "This approach demonstrated a high rate of cellular uptake and a significant reduction of more than 80% in TyRP-1 protein levels, which is involved in the autoimmune destruction of melanocytes, thus showing great promise for topical therapy of vitiligo." (PMID 39339239, 2024). "A notable example is the use of nanodispersions for the delivery of siRNA targeting tyrosinase (TyRP-1) in the treatment of vitiligo." (PMID 39339239, 2024). "Additional instability of tyrosinase-related protein-1 (TYRP1), which is required for melanogenesis, leads to accumulation of melanin intermediates in patients with vitiligo." (PMID 35884944, 2022). "Ultimately, TYR, TYRP1, DCT, and LARP7 have been screened as candidate biomarkers associated with vitiligo." (PMID 34107850, 2021). "Both vitiligo associated genes (PMEL, TYRP1, DCT & MLANA) and PD-L1 had mRNA levels near the median value observed across the dataset." (PMID 30832716, 2019). "Next we performed MICA/MICB immunofluorescence staining on sections from vitiligo and control biopsy samples together with the melanocyte marker TYRP1." (PMID 30515176, 2018). "Most of the down-regulation of melanocyte-related genes (such as Tyr, TYRP1) in the well-established vitiligo lesional skin (LS) most likely is the result of melanocyte death in the lesional skin." (PMID 23251420, 2012). "In support of this data, it was demonstrated that immunizing mice with human tyrosinase-related Protein 2 or utilizing the vaccinia virus to deliver their own tyrosinase-related Protein 1 prompts the development of vitiligo and imparts a shield of defense against melanoma." (PMID 38392077, 2024). "TYR, TYRP1, DCT, and LARP7 were selected as biomarkers associated with vitiligo." (PMID 34107850, 2021). "ABs were released from the apoptosis of PIG3V cells (the immortalized vitiligo epidermal melanocytes) during oxidative stress, and vitiligo autoantigens including tyrosinase-related protein 1 (TYRP-1) and the cleaved nuclear membrane antigen Lamin A (Asp230) are concentrated in the ABs." (PMID 34745423, 2021). "In summary, we found that TYR, TYRP1, DCT, and LARP7 are biomarkers associated with vitiligo." (PMID 34107850, 2021). "Moreover, DCT, TYR, EDNRB and TYRP1 have also been reported previously playing a vital role in vitiligo." (PMID 32509450, 2020). "Several melanocyte autoantigens have been detected in vitiligo patients including tyrosinase, tyrosinase-related protein 1, tyrosinase-related protein 2, melanosomal matrix protein gp 100 (Pmel17), melanocyte transcription factor (SOX10), and melanin concentrating hormone receptor 1 (MCHR1)." (PMID 29362715, 2017). "ApoBDs isolated from an immortalized human vitiligo melanocyte cell line showed that antigen Tyrosinase-related protein 1 (TyrP-1) and cleavage nuclear membrane antigen Lamin A/C (Asp230) are concentrated in ApoBDs, suggesting that ApoBDs may play a key role in the immune destruction of vitiligo." (PMID 37434199, 2023).
vitiligo (continued). "Therefore, other differential genes which were enriched along with WNT6, DCT, TYR, EDNRB and TYRP1 by GO could provide more insights on vitiligo prognosis." (PMID 32509450, 2020). "As expected, the expression of MC1R, TYR, TYRP1, and DCT was significantly downregulated during vitiligo pathogenesis." (PMID 38159176, 2024). "Herein, TYR, TYRP1, DCT, and LARP7 were chosen as biomarkers to identify vitiligo by combining machine learning algorithm and WGCNA." (PMID 34107850, 2021). "TYR, TYRP1, TYRP2, and DCT mRNA levels in vitiligo patients are significantly downregulated and can lead to decreased melanin synthesis." (PMID 34107850, 2021). "Another study on melanocyte autophagy found that the expression of MITF, TYR, TYRP1, and TYRP2 proteins decreased in vitiligo patients." (PMID 34107850, 2021). "Similarly, in vitiligo, CD8+ T cells target antigens from melanosomal proteins such as PMEL, MLANA/MART1, TYR, TYRP1, and DCT." (PMID 37339630, 2023). "TYR, TYRP1, DCT and LARP7 were identified as vitiligo-related biomarkers." (PMID 34107850, 2021). "Previous studies have reported that melanocyte signal pathway is one of the core signal pathways in vitiligo, dominating melanocyte production, destruction, and pigment transport as transcription factors of melanocyte signal pathway, TYR, TYRP1, and DCT involved in vitiligo progression." (PMID 34107850, 2021). "TYR, TYRP1, DCT, and LARP7 were involved in the pathogenesis of vitiligo." (PMID 34107850, 2021). "In control skin and in vitiligo non-lesional skin, most of the melanocytes were devoid of LC3 dots, whereas in the vitiligo lesions, the scarce remaining melanocytes with weak TYRP1 staining showed an LC3 pattern characteristic for autophagy." (PMID 30515176, 2018).
oculocutaneous albinism type 3 (16 papers, 2007 to 2026). Type 3 oculocutaneous albinism (OCA3) is a form of oculocutaneous albinism (OCA) characterized by rufous or brown albinism and occurring mainly in the African population. "Mutations in the TYRP1 gene are associated with various pigment deposition disorders, most notably oculocutaneous albinism type 3 (OCA3), which is characterized by reduced pigmentation in the skin, hair, and eyes." (PMID 41464906, 2025). "Homozygous or compound heterozygous mutations in TYRP1 are associated with oculocutaneous albinism type 3 (OCA3) (OMIM #203290), a milder form of OCA." (PMID 38028607, 2023). "Oculocutaneous albinism type 3 (OCA3) is an autosomal recessive disorder caused by mutations in the TYRP1 gene." (PMID 34638544, 2021). "Mutations in the Tyrp1 gene (TYRP1) can lead to oculocutaneous albinism type 3 (OCA3), an autosomal recessive disease." (PMID 34638544, 2021). "In humans, mutations in the TYRP1 gene are known to cause oculocutaneous albinism type 3 (OMIM 203290)." (PMID 33503951, 2021). "In humans, mutations in Tyrp1 lead to oculocutaneous albinism type 3." (PMID 40709436, 2025). "TYRP1 gene mutation causes oculocutaneous albinism type 3 (OCA3)." (PMID 39228912, 2024). "The TYRP1 gene represents the B locus from classical genetics, and TYRP1 variants have been described in humans with oculocutaneous albinism type III, as well as many animal species with brown coat or feather color, including cats, cattle, chicken, goats, mice, minks, pigs, quail, rabbits and sheep." (PMID 32526956, 2020). "Mutations in TYRP1 can cause oculocutaneous albinism type 3 (OCA3)." (PMID 22457636, 2012). "Of particular note, TYRP1 frameshift mutations, predominately p.N353Vfs*31 (6/7 tumors), were exclusively from one cohort; this variant (rs387906562) has been described as a pathogenic germline variant in oculocutaneous albinism type III, but was only observed as a somatic mutation in these samples." (PMID 35229492, 2022). "Pathogenic variants in Tyrp1 cause oculocutaneous albinism type 3 (OCA3), but the molecular basis by which individual substitutions impair Tyrp1 stability and activity remains incompletely understood." (PMID 42278487, 2026). "Kamaraj and Purohit also showed R326H and R356Q resulting in rigidity of tyrosinase-related protein-1 (TYRP1) protein which might disturb the structural conformation and catalytic function of the structure and also play a significant role in inducing Oculocutaneous albinism type III (OCA3)." (PMID 35547362, 2022).
oculocutaneous albinism (15 papers, 2010 to 2025). Oculocutaneous albinism (OCA) describes a group of inherited disorders of melanin biosynthesis characterized by a generalized reduction in pigmentation of hair, skin and eyes and variable ocular findings including nystagmus, reduced visual acuity and photophobia. "Truncations occurring at similar positions in the TYRP1 protein have been identified in humans and are associated with oculocutaneous albinism." (PMID 36260636, 2022). "Mutations in the TYRP1 gene cause oculocutaneous albinism (OCA3)." (PMID 37628655, 2023). "Although TYRP1 has an undisputed role in melanin synthesis (mutations in the encoding gene cause a form of oculocutaneous albinism, OCA3), its catalytic activity remains unclear." (PMID 36829566, 2023). "Oculocutaneous albinism (OCA) is a genetic disorder caused by mutations in genes involved in melanin synthesis, including Tyr (OCA-1), Oca2 (OCA-2), Tyrp1 (OCA-3), and Slc45a2 (OCA-4)." (PMID 40286213, 2025). "In humans, mutations in TYR result in oculocutaneous albinism (OCA) type 13, whereas mutations in TYRP1 or TYRP2 give rise to OCA type 34 or OCA type 85, respectively." (PMID 37072620, 2023). "Mutations in Tyr and Tyrp1 result in oculocutaneous albinism (OCA1 and OCA3, respectively), a heterogeneous group of congenital developmental pigmentation disorders." (PMID 31947795, 2020). "Mutations in TYR, OCA2, TYRP1, and SLC45A2 are mainly responsible for causing oculocutaneous albinism." (PMID 25093188, 2014).
glaucoma (13 papers, 2006 to 2025). Increased pressure in the eyeball due to obstruction of the outflow of aqueous humor. "DBA/2J mice develop elevated ocular hypertension and glaucoma due to mutations in the Tyrp1 and Gpnmb genes." (PMID 40373024, 2025). "The pigmentary form of glaucoma in DBA/2J mice depends upon mutations in the two melanosomal proteins TYRP1 (tyrosinase-related protein 1) and GPNMB (glycoprotein nmb)." (PMID 25755083, 2015). "Genetic experiments have previously shown that mutations in two genes digenically promote glaucoma in D2 mice, Tyrp1 and Gpnmb." (PMID 18402690, 2008). "It is clear that glaucoma is a multifactorial disease and D2 mice are likely to have susceptibility factors in addition to those associated with the Gpnmb and Tyrp1 genes." (PMID 17608931, 2007). "To examine the effects of low-grade chronic injury, we used the DBA/2J mouse model of glaucoma, in which mutations of two genes (Tyrp1 and Gpnmb150) cause iris pigment dispersion and subsequent elevation of intraocular pressure beginning at approximately 6 months of age." (PMID 29209164, 2017). "Furthermore, it is also unknown whether the Gpnmb and Tyrp1 mutations are sufficient to elicit the D2 form of glaucoma, or whether additional alleles are necessary during distinct stages of disease." (PMID 16827931, 2006). "We address this using DBA/2J mice, a widely used and extensively characterized mouse model of glaucoma that develops age-related OHT due to mutations in two genes: glycosylated protein nmb (Gpnmb) and tyrosinase-related protein 1 (Tyrp1)." (PMID 40373024, 2025). "These strains further define the relative contributions of the Tyrp1 and Gpnmb genes to the D2 phenotype and will serve as powerful control strains in future studies of glaucoma." (PMID 17608931, 2007). "Although mutations in Gpnmb and Tyrp1 are sufficient to cause iris disease, our previous work indicates that additional D2 specific alleles at other loci are needed for progression to high IOP and glaucoma." (PMID 24678736, 2014). "Two distinct eye diseases produce glaucoma in the DBA/2J strain – iris pigment dispersion syndrome, which was mapped to a null mutation in GPNMB, and iris stromal atrophy, which was mapped to a mutation in TYRP1." (PMID 18822132, 2008). "Despite these findings, the cellular mechanisms by which Tyrp1 and Gpnmb contribute to the glaucoma remain largely unknown." (PMID 16827931, 2006). "Future studies of these rare variants have the potential to provide more general insights about TYRP1 and LYST protein function and biological pathways that are important in pigmentation, PDS, and the development of glaucoma." (PMID 34174832, 2021). "These strains provide a powerful resource for studying the functions of Tyrp1 and Gpnmb, dissecting the molecular mechanisms by which pigment dispersion leads to IOP elevation, and identifying additional genes contributing to the D2 form of glaucoma." (PMID 16827931, 2006). "Combined, the analysis of optic nerves from these cohorts of B6.Tyrp1isa GpnmbR150X mice convincingly shows that on the B6 genetic background, the Tyrp-1 and Gpnmb-mediated iris disease does not result in glaucoma." (PMID 16827931, 2006). "This may be a very rare case of glaucoma due to the mutant Tyrp1 gene, or more likely age-related damage that is not related to glaucoma as a similar degree of damage is observed in other non-glaucomatous mouse strains of a similar age." (PMID 17608931, 2007). "Therefore, Tyrp1 is unlikely to be relevant in the BMC mediated glaucoma phenotype of D2 mice." (PMID 18402690, 2008).
iris disease (10 papers, 2006 to 2021). "Mutations in two D2 genes [tyrosinase-related protein 1, Tyrp1, and glycoprotein (transmembrane) nmb, Gpnmb] induce the depigmenting iris disease." (PMID 24678736, 2014). "These experiments demonstrate that the loss of adaptive immune reactions has no influence on the age of onset, rate of progression, or final severity of the iris disease mediated by Tyrp1 and Gpnmb mutations." (PMID 18402690, 2008). "On a D2 background, mutations in Tyrp1 and Gpnmb underlie a form of pigmentary glaucoma involving a pigment-dispersing iris disease, increased IOP, and optic-nerve disease." (PMID 16827931, 2006). "B6 double-congenic mice carrying D2-derived Gpnmb and Tyrp1 mutations develop a D2-like iris disease." (PMID 16827931, 2006). "Mutations in two D2 genes [tyrosinase-related protein 1 (Tyrp1) and glycoprotein (transmembrane) nmb (Gpnmb)] have been shown to induce a depigmenting iris disease (hereafter referred to as iris disease) characterized by abnormal liberation of iris pigment into the ocular anterior chamber." (PMID 27483353, 2016). "We have shown previously that mutations in two genes, Gpnmb and Tyrp1, initiate the iris disease." (PMID 17608931, 2007). "Furthermore, the timing and severity of pigment dispersing iris disease in the double-congenic B6.Tyrp1bGpnmbR150X mice is essentially the same as in D2 mice mutant for the same Tyrp1 and Gpnmb alleles." (PMID 16827931, 2006). "Mutant alleles of the Gpnmb and Tyrp1 genes are necessary for the iris disease, but it is unknown whether alleles of other D2 gene(s) are necessary for the distinct later stages of disease." (PMID 16827931, 2006). "B6 single-congenics with only the Gpnmb and Tyrp1 mutations develop milder forms of iris disease." (PMID 16827931, 2006). "This is likely to be because, in D2 mice, a digenic combination of mutant Tyrp1 and mutant Gpnmb is responsible for earlier onset and a more severe iris disease, which impacts both the iris pigment epithelium and the iris stroma." (PMID 27483353, 2016). "We have previously ruled out components of adaptive immunity (T and B cells) as necessary in the propagation of Tyrp1 and Gpnmb induced iris disease." (PMID 24678736, 2014). "The iris disease of DBA/2J mice is caused by digenic interaction of two genes encoding proteins found within melanosomes, Tyrp1 and Gpnmb, and can be rescued by mutations that decrease pigment production." (PMID 20617205, 2010). "Our consideration of candidates capable of mediating this influence was based in part on previous genetic experiments demonstrating that the D2 iris disease is initiated by the digenic interaction of the Tyrp1 and Gpnmb genes." (PMID 18402690, 2008). "We next took advantage of the B6 background to perform strain controlled genetic epistasis experiments that tested mechanisms contributing to the Tyrp1 and Gpnmb mediated iris disease." (PMID 16827931, 2006). "The current experiments demonstrate that melanosomal defects associated with melanin synthesis play a key role in the initiation of both Tyrp-1 and Gpnmb-mediated iris disease." (PMID 16827931, 2006). "This iris disease is linked to recessive mutations in tyrosinase-related protein 1 (Tyrp1) and glycoprotein nonmetastatic melanoma B (Gpnmb)." (PMID 34366851, 2021). "DBA/2J has two mutated genes, tyrosinase-related protein 1 (Tyrp1) and glycoprotein non-metastatic melanoma protein B (Gpnmb), causing iris disease and IOP elevation that results in progressive RGC degeneration and atrophy of optic nerve." (PMID 25536045, 2014). "Specifically, the iris disease found in D2 mice—due to mutations in both Tyrp1 and Gpnmb—is not rescued by introgression of the mutant genes on to a B6 background." (PMID 21976956, 2011).
iris disease (continued). "A significant result in understanding the Tyrp1 and Gpnmb mediated iris disease is that modulating pigment production with tyrosinase (Tyr, a gene essential for pigment production) and hypopigmentation mutations completely rescues iris atrophy and pigment dispersion." (PMID 16827931, 2006). "These experiments also suggest that the cytotoxicity mediated by Tyrp1 and Gpnmb does not kill the RGCs, and that iris disease and RGC death can be dissociated from each other." (PMID 16827931, 2006).
metastatic melanoma (9 papers, 2007 to 2024). A melanoma that has spread from its primary site to another anatomic site. "Previous studies demonstrated that TYRP1 is linked to a poor clinical outcome for patients diagnosed with metastatic melanoma." (PMID 33869027, 2021). "TYRP1 is also a tumor antigen expressed in over 60% of cutaneous metastatic melanomas (internal analysis) and in 60–90% of uveal and sinonasal melanomas." (PMID 38577337, 2024). "This first-in-human (FIH) phase 1 dose-escalation study characterized the safety, tolerability, maximum tolerated dose/optimal biological dose, and pharmacokinetics (PK) of TYRP1-TCB in patients with metastatic melanoma (NCT04551352)." (PMID 38577337, 2024). "Elevated TYRP1 mRNA levels were detected in metastatic melanoma biopsies, and correlated with poor overall patient survival." (PMID 31624899, 2020). "Additionally, the potential of TYRP1 as a therapeutic target is being explored in a clinical trial testing RO7293583, an investigational drug for TYRP1-positive unresectable metastatic melanomas (NCT04551352)." (PMID 39943991, 2024). "Hence, antibody-engineered marrow macrophages/monocytes in marrow with SIRPα-blockade and clinically relevant anti-Tyrp1 can in principle out-compete and thereby repress human metastatic melanoma." (PMID 35454837, 2022). "TYRP1 expression was negatively correlated with survival time in patients with metastatic melanoma." (PMID 35619714, 2022).